UBE2N (ubiquitin conjugating enzyme E2 N)
Diseases named in the same sentence as UBE2N in open-access papers (continued):
Sharing a sentence is not in itself a finding about the gene and the disease.
prostate carcinoma (4 papers, 2019 to 2025). A carcinoma that arises from epithelial cells of the prostate gland. "These two studies foremost examined the association between UBE2N and prostate cancer, but the elucidation of UBE2N function on prostate cancer cells remains elusive." (PMID 38715121, 2024). "Our current work highlighted abnormally high expression of ubiquitin ligase UBE2N in prostate cancer cells associated with poor prognosis and cell viability and glycolysis." (PMID 38715121, 2024). "Ubiquitin-conjugating enzyme E2 E2 (UBE2E2), and UBE2N were upregulated in prostate cancer and linked to hypoxia signaling." (PMID 30972102, 2019). "Recent findings indicate that the upregulation of UBE2N correlates with poor prognosis in prostate cancer, and that the knockdown of UBE2N inhibits cell viability and glycolysis in prostate cancer cells." (PMID 40771930, 2025). "Immunofluorescence showed that shUBE2N-xenograft presented decreased PCNA-positive cells than shNC-xenograft, suggesting that knockdown of UBE2N suppresses prostate cancer tumor growth in vivo." (PMID 38715121, 2024). "UBE2N knockdown or overexpression was used to analyze its role in cell viability and glycolysis of prostate cancer cells and tumor growth." (PMID 38715121, 2024). "The purpose of this paper is to explore the function and mechanism of UBE2N in prostate cancer cells." (PMID 38715121, 2024). "The result of the GSEA displayed the positive correlations between UBE2N expression and “HALLMARK_GLYCOLYSIS”, “KEGG_OXIDATIVE_PHOSPHORYLATION”, “REACTOME_SIGNALING_BY_WNT”, or “HALLMARK_MYC_TARGETS_V1” in patients with prostate cancer." (PMID 38715121, 2024). "Ubiquitin-conjugating enzyme E2 N (UBE2N) is recognized in the progression of some cancers; however, little research has been conducted to describe its role in prostate cancer." (PMID 38715121, 2024). "Results showed that UBE2N was much higher in prostate cancer and tumor cells than in adjacent normal tissues and normal prostatic epithelial cell lines." (PMID 38715121, 2024). "In this study, we first analyzed RNA sequencing data for the mRNA expression of UBE2N from the TCGA database and the relative mRNA and protein expression of UBE2N in prostate cancer patients’ tissues and tumor cell lines." (PMID 38715121, 2024). "The oncogenic properties of UBE2N were proved in xenograft mice to promote tumor growth and cell proliferation, making it a potential target for treatment for prostate cancer and dramatically improve patient survival." (PMID 38715121, 2024). "Our work suggested that in prostate cancer cells with UBE2N knockdown, glycolysis rate and ATP level were also significantly decreased." (PMID 38715121, 2024). "Given the reported action of UBE2N on cancer progression in the literature, we explored the effect of this gene on prostate cancer cell growth." (PMID 38715121, 2024). "We have a remarkable finding that UBE2N promotes glycolysis in prostate cancer cells, evidenced by increased ECAR, ATP and lactate production." (PMID 38715121, 2024). "UBE2N knockdown inhibited cell viability and glycolysis in prostate cancer cells and restricted tumor formation in tumor-bearing mice." (PMID 38715121, 2024). "UBE2N was upregulated in prostate cancer and the UBE2N-high expression correlated with the poor prognosis of prostate cancer." (PMID 38715121, 2024). "In conclusion, the present results emphasize UBE2N functions in regulating glycolysis and viability of prostate cancer cells." (PMID 38715121, 2024). "Abnormally high expression of UBE2N acts as a cancer promoter to strengthen glycolysis and viability of prostate cancer cells." (PMID 38715121, 2024). "Correlation analysis showed that UBE2N protein expression was negatively correlated with Axin1 protein expression in patients with prostate cancer." (PMID 38715121, 2024). "UBE2N could promote cell survival and glycolysis by activating the Wnt/β-catenin signal in prostate carcinoma." (PMID 40861472, 2025).
prostate carcinoma (continued). "Additionally, UBE2N promotes the ubiquitination and degradation of Axin1, and the overexpression of Axin1 negates the effects of UBE2N on the viability and glycolysis of prostate cancer cells." (PMID 40771930, 2025). "In prostate cancer, the high expression of UBE2N predicted a poor prognosis for patients." (PMID 40861472, 2025). "UBE2N protein expression in prostate cancer tissue microarrays was examined by IHC staining." (PMID 38715121, 2024). "Our findings approve UBE2N as a promising treatment target for prostate cancer." (PMID 38715121, 2024). "However, few works have been conducted to clarify the role of UBE2N in Axin1 stability and Wnt/β-catenin pathway activation, especially in prostate cancer." (PMID 38715121, 2024). "However, little is known about the physiological function of UBE2N in prostate cancer, and the possible mechanism of UBE2N in the process of tumor progression needs further investigation." (PMID 38715121, 2024). "Therefore, we hold the opinion that UBE2N acts as a promoter for prostate cancer cell viability via enhancing intracellular glycolysis." (PMID 38715121, 2024). "Therefore, we further investigated the efect of UBE2N on the development of prostate cancer." (PMID 38715121, 2024). "The increases of UBE2N mRNA and protein expressions were also found in DU145, LNCAP, PC3, and 22RV1 prostate cancer cell lines." (PMID 38715121, 2024). "UBE2N expression was detected in Cancer Genome Atlas Prostate Adenocarcinoma (TCGA-PRAD) data, prostate cancer tissue microarrays, and prostate cancer cell lines, respectively." (PMID 38715121, 2024).
cervical carcinoma (3 papers, 2021 to 2023). A carcinoma arising from either the exocervical squamous epithelium or the endocervical glandular epithelium. "UBE2N levels are elevated in cervical carcinoma, and patients with high expression of UBE2N had a poorer OS than patients with low expression." (PMID 34199813, 2021). "The overexpression of miR-590-3p inhibited cervical carcinoma cell growth, which was rescued by the upregulation of UBE2N." (PMID 34199813, 2021). "Furthermore, the study showed a negative correlation between the expression of microRNA (miR)-590-3p and UBE2N in cervical carcinoma—miR-590-3p directly targeted UBE2N and inhibited its expression in cervical carcinoma." (PMID 34199813, 2021). "Thus, this study demonstrated that targeting the miR-590-3p/UBE2N axis could be a potential strategy for the treatment of cervical carcinoma." (PMID 34199813, 2021). "Knockdown of UBE2N inhibited the activation of MEK1/2 and p38 in cervical carcinoma cells and strongly suppressed cervical carcinoma cell growth." (PMID 34199813, 2021).
Hypoglycemia (3 papers, 2021 to 2022). A decreased concentration of glucose in the blood. "At hypoglycemia, UBE2N, STIP1, and UBE2L3 increased in T2D compared to baseline (p < 0.05, p < 0.05, and p < 0.05, respectively), a change not seen in controls." (PMID 34831332, 2021). "At hypoglycemia, UBE2N, STIP1, and UBE2L3 increased (all p < 0.05), whilst TLR4:MD-2 and HSPA8 decreased (p < 0.05) in T2D versus baseline." (PMID 34831332, 2021). "In the time course following hypoglycemia, UBE2N, UBE2L3 and STIP1 were significantly and persistently higher in T2D compared to normal controls for up to 24-h, suggesting that in T2D the heat shock and related proteins are preconditioned for an enhanced response." (PMID 34426634, 2021). "In the post-hypoglycemia follow-up period, most proteins normalized to baseline by 24-h; however, STIP1 (p = 0.003), UBE2N (p = 0.004) and UBE2L3 (p < 0.04) were decreased in controls at 24-h." (PMID 34426634, 2021). "In accord with the findings in severe hypoglycemia, there were significant increases in UBE2N, STIP1, and UBE2L3 seen in hypoglycemia only in the T2D cohort that returned to baseline by 24 h." (PMID 34831332, 2021). "UBE2N (RFU): 3645.6 ± 211.2 vs 2931.4 ± 121.5, 0.5-h post-hypoglycemia, p < 0.05; 3925.6 ± 365.8 vs 2973.2 ± 151.4, 1 h post-hypoglycemia, p < 0.01; 3640.5 ± 263.8 vs 2983.3 ± 190.4, 2 h post-hypoglycemia, p < 0.01)." (PMID 34426634, 2021). "UBE2N and STIP1 were higher from 0.5-h to 2 h post-hypoglycemia in T2D compared to control." (PMID 34426634, 2021). "Notably UBE2N, UBE2L3, and STIP1 all significantly go down in controls but not at all in T2D in response to hypoglycemia, whilst the protein that is linked within the system, UBE2G2, was unaffected by hypoglycemia, though significantly lower than levels seen in T2D at all time points." (PMID 34426634, 2021). "Why the levels of UBE2N, UBE2L3 and STIP1 should fall in the control subjects in response to hypoglycemia, whilst UBE2G2 showed no apparent change in level, is unclear, and whether the loss of regulation of these specific and tightly controlled proteins would lead to a detrimental effect is unknown." (PMID 34426634, 2021).
lung carcinoma (3 papers, 2023). "In this study, we found that UBE2N was increased in lung cancer cell lines." (PMID 37724906, 2023). "Thus, we concluded that ALDOC regulates the proliferation, migration, and apoptosis of lung cancer cells via targeting UBE2N." (PMID 37724906, 2023). "Silencing UBE2N achieved the same effects on lung cancer cells as knocking down ALDOC." (PMID 37724906, 2023). "Furthermore, silencing UBE2N achieved the same effects on lung cancer cells as knocking down ALDOC." (PMID 37724906, 2023).
acute lymphoblastic leukemia (2 papers, 2014 to 2025). Leukemia with an acute onset, characterized by the presence of lymphoblasts in the bone marrow and the peripheral blood. "Furthermore, in acute lymphoblastic leukemia models, UBE2N may be a key node of oncogenic immune signaling, as blocking its mediated ubiquitination of innate immune molecules can inhibit its oncogenic function." (PMID 40861472, 2025).
atherosclerosis (2 papers, 2020 to 2021). A disease characterized by the build-up of fatty material and calcium deposition in the arterial wall resulting in partial or complete occlusion of the arterial lumen. "Our study identified seven core genes (UQCR11, UBE2N, ADD1, TLN1, IRAK3, LY96, and MAP3K1) that are strongly linked to FH and lead to a higher risk of atherosclerosis." (PMID 32760426, 2020). "Through analysis of the public database, seven hub genes (UQCR11, UBE2N, ADD1, TLN1, IRAK3, LY96, and MAP3K1) have recently been found to be strongly associated with familial hypercholesterolemia and contribute to a higher risk of atherosclerosis." (PMID 34895070, 2021).
leukemia (2 papers, 2014 to 2025). A malignant (clonal) hematologic disorder, involving hematopoietic stem cells and characterized by the presence of primitive or atypical myeloid or lymphoid cells in the bone marrow and the blood. "Given the increase in immunoproteasome activity and dependency in AML and the resulting broader degradation of critical proteins, our data suggest that coactivation of UBE2N is required in these leukemias to regulate proteostasis of oncogenic pathways by stabilizing critical proteins." (PMID 40371639, 2025). "Inhibiting UBE2N selectively degrades these proteins, suppressing leukemia." (PMID 40371639, 2025). "Moreover, inhibiting UBE2N has been shown to suppress cancer cell growth in several solid cancers and various types of leukemia and lymphoma." (PMID 40371639, 2025). "Despite the significance of UBE2N in AML, the precise mechanistic basis for its dependency in these leukemias has remained unknown." (PMID 40371639, 2025).
myelodysplastic syndrome (2 papers, 2020 to 2025). A clonal hematopoietic disorder characterized by dysplasia and ineffective hematopoiesis in one or more of the hematopoietic cell lines. "Ubiquitin-conjugating enzyme E2 N (UBE2N) has been identified as a novel therapeutic target in myelodysplastic syndrome (MSD) and AML." (PMID 32674429, 2020). "We recently reported that inhibiting UBE2N with a selective small molecule inhibitor can suppress myelodysplastic syndrome (MDS) and AML cells." (PMID 40371639, 2025).
Atrophy (1 paper, 2024). Any weakening or degeneration, especially through lack of use. "Therefore, the two-step mechanism of UBE2W and UBE2N/V could play an important role in regulating the function of MuRF1 during denervation-induced muscle atrophy." (PMID 38283190, 2024).
Autoimmunity (1 paper, 2023). The occurrence of an immune reaction against the organism's own cells or tissues. "We detected strong expression of LTA, TTC4 and UBE2N from the maternal genome and moderate expression of numerous other genes involved in autoimmunity, based on “PubMed” enrichment analysis with STRING17." (PMID 37488170, 2023).
Azoospermia (1 paper, 2022). Absence of any measurable level of sperm,whereby spermatozoa cannot be observed even after centrifugation of the semen pellet. "Regarding the reproductive system, three of these genes (UBE2N, PPP2R1B and ACVR2A) have been shown to be involved in reproductive disfunctions in humans (polycystic ovary syndrome and transsexuality, azoospermia, and susceptibility to preeclampsia, respectively." (PMID 36340025, 2022).
breast adenocarcinoma (1 paper, 2025). "Mutations in the NOD1/2 signaling pathway and in DNA binding transcription factor activity, affecting genes such as MAP3K7, UBE2N, IKBKG, CHUK, and IKBKB, occurred late in breast adenocarcinoma and ovarian adenocarcinoma." (PMID 39868264, 2025).
breast invasive carcinoma (1 paper, 2023). "We found that the FTD DEGs, AKT3, UBE2N, VDAC1, ADCYAP1R1, C4A, and GFAP showed significant comorbidity in breast invasive carcinoma patients at a p-value < 0.05." (PMID 37834358, 2023).
diffuse intrinsic pontine glioma (1 paper, 2023). A neuroglial tumor that arises from the middle portion of the brain stem. "A knockout screen on tumour sphere cells derived from diffuse intrinsic pontine glioma also ranked knockout of UBE2N, CHD4 and EED as a hit in combination with the histone deacetylase inhibitor panobinostat." (PMID 37161535, 2023).
endothelial dysfunction (1 paper, 2025). In vascular diseases, endothelial dysfunction is a systemic pathological state of the endothelium (the inner lining of blood vessels) and can be broadly defined as an imbalance between vasodilating and vasoconstricting substances produced by (or acting on) the endothelium. "Together, these results suggest that the SND1/UBE2N/RNF8-RNF168 axis is crucial in protecting against sunitinib-induced endothelial dysfunction by regulating the DDR pathway." (PMID 39895626, 2025). "Having shown that SND1 regulates expression of UBE2N in ECs, we tested the notion that UBE2N acts downstream of SND1 and is implicated in sunitinib-induced endothelial dysfunction." (PMID 39895626, 2025). "Hence, we asked whether impaired UBE2N-mediated DNA repair contributes to sunitinib-induced endothelial dysfunction in hiPSC-ECs." (PMID 39895626, 2025). "With this approach, we revealed translational regulation of SND1 as a key mediator of sunitinib-induced endothelial dysfunction, which suggests that targeting SND1 translation and the SND1 downstream factors UBE2N, RNF8, and RNF168 is a potential therapeutic strategy for vascular dysfunction." (PMID 39895626, 2025). "Furthermore, wound-healing assays revealed that the protective effects of UBE2N OE on sunitinib-induced endothelial dysfunction were reversed by inhibition of RNF8 or RNF168 but not HLTF and SHPRH." (PMID 39895626, 2025).
gynecologic cancers (1 paper, 2025). "While the oncogenic roles of UBE2N and tumor-derived EVs have been previously reported, our work is the first to demonstrate a functional role for UBE2NL and HIST2H3PS2, particularly in the context of EV-mediated tumor progression in gynecologic cancers." (PMID 40429973, 2025).
ischemia (1 paper, 2023). A hypoperfusion of the BLOOD through an organ or tissue caused by a PATHOLOGIC CONSTRICTION or obstruction of its BLOOD VESSELS, or an absence of BLOOD CIRCULATION. "The neuroprotective effect of nonspecific HDACis in models of ischemia, oxidative stress, and glutamate neurotoxicity is associated with the transcriptional suppression of pro-apoptotic factors, such as p75(NTR)-dependent caspase-3 and ubiquitin-conjugating enzyme E2N Ube2n." (PMID 37296584, 2023).
Listeria monocytogenes infections (1 paper, 2024). "Notably, UBE2N has been shown to be involved in ubiquitination of β-actin and is recruited to actin-rich structures in Listeria monocytogenes infections." (PMID 39526800, 2024).
mesothelioma (1 paper, 2018). A usually malignant and aggressive neoplasm of the mesothelium which is often associated with exposure to asbestos.
metastatic tumors (1 paper, 2024). "The expression of various antioxidants, including PRX1, GPX1, UBE2N, and AIF1, was significantly higher in metastatic tumors." (PMID 39795567, 2024).
osteoporosis (1 paper, 2019). A condition of reduced bone mass, with decreased cortical thickness and a decrease in the number and size of the trabeculae of cancellous bone (but normal chemical composition), resulting in increased fracture incidence. "Then, three hub genes that have strong protein and protein interactions and might be associated with osteoporosis were identified, including BRCC3, UBE2N, and UBE2K." (PMID 30834083, 2019). "We identified three hub genes that might associate with osteoporosis including BRCC3, UBE2N, and UBE2K." (PMID 30834083, 2019). "The mRNA expressions of UBE2N and UBE2K not changed in osteoblasts from osteoporosis patients compared with healthy donors, while the mRNA expression of BRCC3 was significantly increased." (PMID 30834083, 2019). "UBE2N mRNA and UBE2K mRNA were not changed in osteoblasts isolated from osteoporosis patients, compared with healthy donors, whereas BRCC3 mRNA was significantly increased." (PMID 30834083, 2019).
psoriasis (1 paper, 2020). An autoimmune condition characterized by red, well-delineated plaques with silvery scales that are usually on the extensor surfaces and scalp. "STAT3, p-STAT3, UBE2N and CDK6 are downregulated by the overexpression of hsa-miR-4516, which is consistently upregulated in psoriasis and induces apoptosis in HaCaT cells." (PMID 32785106, 2020).
schizophrenia (1 paper, 2023). A major psychotic disorder characterized by abnormalities in the perception or expression of reality. "A reduction in ubiquitin-conjugating enzyme E2N (UBE2N) in the PFC of patients with schizophrenia was also reported." (PMID 36833173, 2023).